RN7SL678P (RNA, 7SL, cytoplasmic 678, pseudogene)
Gene: Miscellaneous RNA gene on chromosome 21 (37,215,605 to 37,215,903, forward strand). Ensembl gene ENSG00000263969.
Homologues: Orthologues: chimpanzee Metazoa_SRP (98% identical). Paralogues in human: RN7SL1 (85% identical), RN7SL2 (84% identical), RN7SL3 (84% identical), RN7SL278P (83% identical), RN7SL126P (82% identical), RN7SL14P (82% identical), RN7SL664P (82% identical), RN7SL566P (81% identical), RN7SL220P (81% identical), RN7SL296P (81% identical), RN7SL321P (81% identical), RN7SL431P (81% identical), and 704 more.